OR13C4 (olfactory receptor family 13 subfamily C member 4)
Description:
Odorant receptor.
Synonyms: HSHTPCRX17; HTPCRX17; OR2K1; OR37F; OR9-7
Tractability: Antibody: UniProt places it where antibodies can reach, with medium confidence; UniProt predicts a signal peptide or a membrane-spanning region; its Gene Ontology location is reachable by antibodies, with medium confidence.
Gene: Protein-coding gene on chromosome 9 (104,526,253 to 104,527,209, reverse strand). Ensembl gene ENSG00000148136.
Subcellular location: Cell membrane
Pathways (Reactome):
Sensory Perception: Expression and translocation of olfactory receptors
Gene Ontology:
Molecular function: olfactory receptor activity; G protein-coupled receptor activity
Biological process: detection of chemical stimulus involved in sensory perception of smell; G protein-coupled receptor signaling pathway
Cellular component: plasma membrane; membrane
Genetic constraint (gnomAD): Missense variants: 365 observed, 375.59 expected, observed/expected ratio (o/e) 0.97, 90% interval 0.89 to 1.06. Synonymous variants: 131 observed, 139.47 expected, observed/expected ratio (o/e) 0.94, 90% interval 0.81 to 1.09.
Homologues: Orthologues: macaque OR13C4 (94% identical), dog OR13C4 (89% identical), pig OR13C4 (87% identical), guinea pig OR13C4 (84% identical). Paralogues in human: OR13C3 (84% identical), OR13C9 (65% identical), OR2S2 (65% identical), OR13C2 (64% identical), OR13C5 (64% identical), OR13C8 (62% identical), OR13D1 (58% identical), OR2K2 (54% identical), OR13J1 (49% identical), OR10A4 (47% identical), OR2G3 (47% identical), OR2F1 (47% identical), and 80 more.
Diseases named in the same sentence as OR13C4 in open-access papers:
OR13C4 is named in the same sentence as 2 diseases in open-access papers, as found by Europe PMC text mining. Sharing a sentence is not in itself a finding about the gene and the disease.
OR13C4 shares sentences with these, for which no sentence is quoted: pancreatic cancer (1 paper); tumour (1).